BCL2 (BCL2 apoptosis regulator)
Diseases named in the same sentence as BCL2 in open-access papers (continued):
Sharing a sentence is not in itself a finding about the gene and the disease.
Fulminant hepatitis (1 paper, 2015). Acute hepatitis complicated by acute liver failure with hepatic encephalopathy occurring less than 8 weeks after the onset of jaundice. "We then tested an anti-apoptotic therapy using mRNA encoding Bcl-2 in model mice with fulminant hepatitis." (PMID 26507781, 2015). "In conclusion, the hydrodynamic injection of mRNA encoding Bcl-2 with polyplex nanomicelles into the liver of mice with fulminant hepatitis effectively reduced apoptosis of the liver cells." (PMID 26507781, 2015). "When applying mRNA encoding Bcl-2 in a mouse model of fulminant hepatitis, the number of apoptotic liver cells showed a significant decrease compared to the saline control, while pDNA encoding Bcl-2 induced only a minimal therapeutic effect to prevent apoptosis." (PMID 26507781, 2015).
gall bladder adenocarcinoma (1 paper, 2002). "In summary, human HAG-1 gall bladder adenocarcinoma cells are sensitized to apoptosis by taxotere through Bcl-2 phosphorylation as a consequence of activation of Src PTK." (PMID 11875716, 2002).
gallbladder tumor (1 paper, 2014). "To determine whether the impact of oridonin on tumor growth inhibition was related to caspase-3, caspase-9, NF-κB, Bax, Bcl-2, PARP-1 and cytochrome c, we evaluated the levels of these apoptosis-related proteins in the gallbladder tumor tissues by western blot analysis." (PMID 24655726, 2014).
gastrointestinal neuroendocrine tumors (1 paper, 2010).
gestational diabetes (1 paper, 2018). Carbohydrate intolerance first diagnosed during pregnancy. "BCL-2 is an anti-apoptotic protein, and there are established links between gestational diabetes, decreased placental BCL-2 expression and increased apoptosis in trophoblasts." (PMID 29470513, 2018).
gestational trophoblastic disease (1 paper, 2015). "The change of Bcl-2 activity as antiapoptosis and Beclin-1 as proautophagy plays a role in pathogenesis of gestational trophoblastic diseases." (PMID 26494988, 2015).
GNE myopathy (1 paper, 2022). "The mitochondrial membrane potential of myoblasts in patients with GNE myopathy was significantly reduced, Bax expression levels were increased, and anti-apoptotic Bcl-2 expression was decreased, indicating the activation of the mitochondrial apoptosis pathway." (PMID 35904705, 2022). "In a HEK cell–based model of GNE myopathy, mitochondria-dependent apoptosis and IGF-1R phosphorylation were observed, and IGF-1R hyposialylation led to AKT phosphorylation and downregulation of the ERK pathway, which may rescue apoptotic cell death of GNE-deficient cell lines through Bcl-2." (PMID 35904705, 2022).
hamartoma (1 paper, 2015). A benign and excessive tumor-like growth of mature cells and normal tissues which grow in a disorganized pattern. "Thus, immunohistochemical detection of CD34, CD99, and bcl-2 is inefficient in differentiation of hamartoma-like SFTs from pancreatic hamartomas." (PMID 26425382, 2015).
hantavirus infection (1 paper, 2020). "Here, we show that hantavirus infection leads to increased production of the anti-apoptotic protein BCL-2, hampering the permeabilization of mitochondria and thereby blocking downstream signaling and activation of caspases." (PMID 32032391, 2020). "Here we show that hantavirus infection leads to increased production of anti-apoptotic BCL-2, which protects mitochondria from MOMP and release of cyt C, thereby inhibiting intrinsic apoptosis." (PMID 32032391, 2020). "Moreover, we observed increased levels of NFkB (p65) in the nucleus in ANDV- and HTNV-infected cells compared to uninfected cells, suggesting that hantavirus infection triggers NFkB activation, potentially contributing to the observed increased transcription of BCL-2 mRNA." (PMID 32032391, 2020). "However, no clear effect on BCL-2 expression was observed in cells expressing the N protein or the Gn/Gc proteins, and uninfected bystander cells showed similar levels as observed in cells not exposed to hantavirus, indicating that hantavirus infection per se is needed for upregulation of BCL-2." (PMID 32032391, 2020).
hematoma (1 paper, 2018). A hematoma is a collection of blood from a vascular structure into an extravascular space. "Furthermore, SSTR1 co-localized with active-caspase-3 and bcl-2 around the hematoma, while the expression of active-caspase-3 was parallel with that of SSTR1 in a time-dependent manner, indicating that up-regulated SSTR1 contributed to neuronal apoptosis following ICH." (PMID 29522573, 2018).
hemorrhagic fever (1 paper, 2012). An infectious disease caused by certain viruses or bacteria that can damage the walls of tiny blood vessels, making them leak, and can hamper the blood's ability to clot and cause severe, life-threatening illness. "For example, Dengue virus, which can also induce a hemorrhagic fever, was described to decrease the expression of Bcl-2 and Bcl-xL in both mRNA and protein levels." (PMID 22238639, 2012).
hemorrhagic stroke (1 paper, 2020). A stroke caused by a bleed on the brain. "A similar effect was observed in hemorrhagic stroke, where Wnt signaling activation promoted neurogenesis in the SVZ together with Bcl2 and β-catenin expression, suggesting that Wnt signaling plays similar roles in both ischemic and hemorrhagic stroke." (PMID 32708801, 2020).
Hirsutism (1 paper, 2018). Abnormally increased hair growth referring to a male pattern of body hair (androgenic hair). "In addition to validation of SNPs associated with these previous traits, our study identified three novel hirsutism loci that were also eQTLs for BCL2, GCC2 and LIMS1, and TBX15." (PMID 29895819, 2018).
hymenolepiasis (1 paper, 2022). A parasitic infection caused by tapeworms. "The expression of anti-apoptotic protein Bcl-2 in the small intestine varied according to the duration of hymenolepiasis." (PMID 35955110, 2022). "Hymenolepiasis enhanced apoptosis in the small and large intestine of the host by increasing the expression of the pro-apoptotic gene and protein Bax and by decreasing the expression of the anti-apoptotic gene and protein Bcl-2." (PMID 35955110, 2022).
hyper-IgM syndrome (1 paper, 2016). A primary immune deficiency disorder characterized by defective CD40 signaling; via B cells affecting class switch recombination (CSR) and somatic hypermutation. "ELISA was used to determine whether BCL2+IL6+AID− mice exhibited changes in serum Ig patterns that mimic the hyper-IgM syndrome of patients with WM." (PMID 27813533, 2016).
Hyperammonemia (1 paper, 2025). An increased concentration of ammonia in the blood. "Western blots for hepatic bax, bcl-2, diablo, and cleaved caspase-3 proteins confirmed the activation of apoptosis related proteins during hyperammonemia." (PMID 40053595, 2025).
Hyperkeratosis (1 paper, 2025). Hyperkeratosis is a histopathological term defining a thickened stratum corneum and may be present in many different skin conditions, with many possible overlaps. "Among BCL-2 groups, G6 showed the lowest hypertrophy (2.5 ± 0.1) and hyperkeratosis (1.4 ± 0.1), while G5 had the lowest epidermal inflammation (0.2 ± 0.1)." (PMID 40871454, 2025).
Hyperoxaluria (1 paper, 2020). Increased excretion of oxalates in the urine.
hypertriglyceridemia (1 paper, 2023). A laboratory test result indicating elevated triglyceride concentration in the blood. "In univariable analysis, molecular typing, BCL2 fusion translation, ferritin, and BMI were risk factors for hypertriglyceridemia (p <0.05)." (PMID 37384286, 2023).
hyperuricemia (1 paper, 2023). An abnormally high level of uric acid. "Furthermore, as downstream molecules of Bcl‐2 in the apoptosis pathway, we observed elevated proapoptotic BAX and cleaved caspase‐3 levels in the hyperuricemia model." (PMID 37502610, 2023).
Hypokalemia (1 paper, 2021). An abnormally decreased potassium concentration in the blood. "Among BCL2 inhibitors, the majority of toxic events lie within the febrile neutropenia, hypokalemia, or gastric dysfunction." (PMID 34575992, 2021).
hypospadias (1 paper, 2024). Hypospadias is the displacement of the urethral meatus on the ventrum of the penis. "The Akt/Bax/caspase-3 pathway was implicated in regulating apoptosis levels, with increased caspase-3 protein levels and Bax/Bcl-2 ratios, alongside decreased pAkt/Akt ratios, detected in the hypospadias group." (PMID 39698037, 2024).
IgA nephropathy (1 paper, 2012). "Decreased expression of Bcl-2 in podocytes is associated with progressive glomerular injury and clinical indices of poor renal prognosis in human IgA nephropathy." (PMID 22745830, 2012).
Infantile onset (1 paper, 2020). Onset of signs or symptoms of disease between 28 days to one year of life. "Interestingly, one myopathy, Infantile-onset multisystem disease with progressive muscle weakness is caused by mutations in Bit-1/PTRH-2, which controls Bcl-2 expression." (PMID 32366831, 2020).
intestinal cancer (1 paper, 2022). "At the same time, research reports have identified that miR-206 regulates the resistance of intestinal cancer cells to 5-FU by targeting BCL2." (PMID 36115953, 2022).
intestinal polyp (1 paper, 2017). Discrete abnormal tissue masses that protrude into the lumen of the intestine. "The mRNA expression level of Bcl-2 was decreased to 57.7% (p < 0.05) in intestinal polyps compared to the untreated group." (PMID 28420165, 2017).
intestinal schistosomiasis (1 paper, 2010). An intestinal infection that is caused by Schistosoma japonicum. "This supports the contention that evasion of apoptosis through change in the expression of Bcl-2 may be an alternative molecular pathway through which genotoxic agents can induce carcinogenesis in intestinal schistosomiasis." (PMID 20704754, 2010).
intestinal T-cell lymphomas (1 paper, 2022). "All of the epitheliotropic intestinal T-cell lymphomas in this study showed Bcl-2 immunoreaction (22/22)." (PMID 35448666, 2022). "Interestingly, we have observed that feline epitheliotropic intestinal T-cell lymphoma cases with a proliferation index higher than 15% display an intense Bcl-2 immunoreaction in most cases, although the limited sample size precludes a definitive conclusion." (PMID 35448666, 2022). "Future therapeutic approaches targeting Bcl-2 could reduce desmoplasia in feline epitheliotropic intestinal T-cell lymphomas and, therefore, may contribute to improve prognosis and survival in cats." (PMID 35448666, 2022).
intestinal tumour (1 paper, 2016). "Apcfl/fl) to determine the relevance of Bcl-2 for intestinal tumour initiation." (PMID 26956214, 2016).
intrauterine growth restriction (1 paper, 2013). "Importantly, BCL2 is known to be reduced in intrauterine growth restriction, and upregulation of BCL2 in our studies may play a protective role against LTH for fetal lambs." (PMID 24367503, 2013).
IPEX syndrome (1 paper, 2012). "A thymic biopsy showed absent CD1a and increased Bcl-2 (an anti-apoptotic protein) expression, due to a four point mutation in FOXP3 leading to translational frameshift, which is similar to IPEX syndrome." (PMID 22816667, 2012).
iron deficiency (1 paper, 2023). "Further, we tested the expression of Bcl2 and Bax in testis and epididymis to evaluate the effect of iron deficiency on cellular apoptosis." (PMID 37346174, 2023).
iron metabolism disorder (1 paper, 2021). "To investigate the effect of iron metabolism disorder on cell apoptosis and mitochondrial function in the hippocampus and cortex, we tested ROS production and the expression of apoptosis-related protein Bcl2 and Bax, and MMP levels." (PMID 34547719, 2021).
ischemic colitis (1 paper, 2020). Inflammation of the colon due to colonic ischemia resulting from alterations in systemic circulation or local vasculature. "In the present study, induction of ischemic colitis affected the expressions of Bcl-2 and Bax, resulting in decrement of the ratio of antiapoptotic protein Bcl-2 to proapoptotic protein Bax." (PMID 32149087, 2020). "Induction of ischemic colitis increased Bax (24 kDa) and Bcl-2 (26–29 kDa) expressions in the colonic tissues." (PMID 32149087, 2020). "However, the increase of Bax expression was greater than Bcl-2 expression, and consequently, Bcl-2 to Bax ratio was lower in the ischemic colitis-induced rats than in the normal rats (P < 0.05)." (PMID 32149087, 2020). "Apoptosis was increased by decreasing the ratio of Bcl-2 to Bax and by suppressing the phosphorylated form of ERK1/2 expression in the ischemic colitis rats." (PMID 32149087, 2020).
jaw cysts (1 paper, 2020). "OKCs have a typical parakeratotic epithelium demonstrating transepithelial cytokeratin 17 (CK17) and basal bcl2 staining on immunohistochemistry (IHC), which distinguishes them from other common jaw cysts." (PMID 32632899, 2020). "The aim of the present study was to analyse a series of consecutive jaw cysts for their expression of CK17 and bcl2 and assess how these IHC stains may help in their diagnosis." (PMID 32632899, 2020).
kidney stone (1 paper, 2023). "Our findings suggest that BSHS may inhibit kidney stone formation mainly by regulating estrogen and estrogen receptor levels, inhibiting oxidative stress processes, reversing apoptosis, and decreasing CaOx crystals deposition through E2/ESR1/ESR2, NRF2/HO-1, and BCL2/BAX signaling pathways." (PMID 36864834, 2023).
lactic acidosis (1 paper, 2021). Metabolic acidosis characterized by the accumulation of lactate in the body. "Interestingly, in a different study concerning lactic acidosis, it was observed that bcl-2 expression causes a delay in glucocorticoid-induced apoptosis protecting the CCRF-CEM cell line from dexamethasone." (PMID 34072627, 2021).
Li-Fraumeni syndrome (1 paper, 2025).
lumbar disc degeneration (1 paper, 2022). "Bcl-2 is located upstream of related caspases in endogenous apoptosis, and studies have shown that the -938C > A polymorphism of Bcl-2 may be significantly associated with the severity of human lumbar disc degeneration (LDD)." (PMID 36008968, 2022).
lung carcinoids (1 paper, 2021). "In other study showed that bcl2 expression and bcl2/Bax expression level might be beneficial as independent diagnostic factors in lung carcinoids." (PMID 33773561, 2021).
male breast carcinoma (1 paper, 2014). A malignant neoplasm involving the male breast. "An example of this is Bcl-2, which is an inhibitor of apoptosis, and has also been found to be overexpressed in male breast cancer." (PMID 23755153, 2014). "Bcl-2 has been shown to correlate with low mitotic cell count and lower grade tumors, suggesting it can be an important biomarker in male breast cancer pathogenesis." (PMID 23755153, 2014).
malignant meningioma (1 paper, 2021). "Since the main target molecules of navitoclax are Bcl-2 and Bcl-xL, we investigated which is the primary target of navitoclax in senescent malignant meningioma cells." (PMID 34765973, 2021).
mast cell tumors (1 paper, 2019). "A previous report evaluated Bcl-2 expression in mast cell tumors and observed increased levels of anti-Bcl-2 at D28 after ECT and then decreased expression at D4619." (PMID 31676831, 2019).
metastatic prostate carcinoma (1 paper, 2023). A carcinoma that arises from the prostate gland and has spread to other anatomic sites. "Docetaxel is used to treat metastatic prostate cancer and exerts its activity through stabilization of microtubules and induction of BCL-2 phosphorylation, resulting in G2/M arrest, mitotic catastrophe, and apoptosis." (PMID 37464317, 2023).
monocytic leukemia (1 paper, 2024). "The investigators proved that monocytic leukemia blasts lose expression of the Venetoclax target Bcl-2 while Myeloid cell leukemia‐1 (MCL-1) protein, an antiapoptotic member of the Bcl-2 family expression is significantly higher in FAB-M5 patients." (PMID 39035053, 2024).
motor neuron disease (1 paper, 2018). "After addressing several issues such as protein expression efficacy and final yield of the fusion protein, we expect to confirm the anti-apoptotic effect of the Bcl-2-TTC fusion protein in animal models of neurological diseases, such as motor neuron disease." (PMID 29890980, 2018).
mucinous ovarian tumors (1 paper, 2012).
mucositis (1 paper, 2025). Mucositis is inflammation and damage of the mucous membranes lining the mouth and other parts of the gastrointestinal (GI) tract. "Building on this, we hypothesize that HDZJF may improve radiation-induced mucositis by modulating multiple key molecules, such as EGFR, PI3K, AKT, and downstream targets like NF-κB, BAX, and BCL-2." (PMID 40129983, 2025).
multicystic dysplastic kidney (1 paper, 2011). Multicystic dysplastic kidney (MCDK) is a congenital anomaly of the kidney and urinary tract (CAKUT) in which one or both kidneys (unilateral or bilateral MCDK respectively) are large, distended by multiple cysts, and non-functional. "In our study, however, BCL-2 was present and stained the cytoplasm of the dysplastic tubules of 8 out of 10 cases of obstructive and all nonobstructive multicystic dysplastic kidneys." (PMID 21689023, 2011). "We expected therefore that BCL-2 should be markedly decreased or even absent in the dysplastic parenchyma and tubules of multicystic renal dysplasia." (PMID 21689023, 2011).
multinodular goiter (1 paper, 2015). Nodular goiter characterized by more than one discrete tissue mass. "Separate analysis of a subset of the multinodular goiter samples with more aggressive PTC subtypes revealed 2 - 4-fold upregulation in the levels of CHEK1, c-MET and TIMP1, and a 2-4-fold downregulation of BCL2, c-KIT, TG and PPARγ (lower part)." (PMID 25868389, 2015).
muscle atrophy (1 paper, 2020). The loss of muscle tissue due to inactivity or disease. "In summary, we identified miR‐29b‐3p as a muscle atrophy‐associated exosomal miRNA with potential to be uptake by neuronal cells which consequently inhibits neuronal cell differentiation via targeting the mRNAs of c‐FOS, BCL‐2, RIT1, LAMC1, and upregulation of lncRNA HIF1α‐AS2." (PMID 32233025, 2020).
mycoplasmal pneumonia (1 paper, 2020). "mRNA and protein expressions of apoptosis-related factors Bax and Bcl-2 were measured by qRT-PCR and Western blot in order to investigate how miR-143-3p mediated TLR4/MyD88/NF-κB signaling pathway to work on the apoptosis of alveolar epithelial cells of mice with mycoplasmal pneumonia." (PMID 32597476, 2020).